FGF21 (fibroblast growth factor 21)
Diseases named in the same sentence as FGF21 in open-access papers (continued):
Sharing a sentence is not in itself a finding about the gene and the disease.
colitis (continued). "However, the protective effects of FGF21 KO against DSS-induced colitis and the colonic phosphorylation of STAT3 cannot be explained by the IL-6 regulation since IL-6 expression was reduced in the KO mice." (PMID 37432218, 2023). "Using FGF21 knockout mice, our study demonstrated that experimental colitis-associated eWAT loss is attenuated when FGF21 is absent." (PMID 28584524, 2017). "Our results showed that FGF21 induction is a negative factor in adipose lipolysis in DSS-induced colitis, which is known as an inflammatory-associated disorder." (PMID 28584524, 2017). "This elevation implies a possible role of FGF21 in DSS-induced colitis." (PMID 28584524, 2017). "Next, we examined whether neutralization of circulating FGF21 could also inhibit colitis-induced lipolytic enzyme activation in eWAT." (PMID 28584524, 2017). "We hypothesized that FGF21 plays an important role in adipose tissue lipolysis in animals during acute colitis to regulate the local supply of energy." (PMID 28584524, 2017). "We examined whether increased FGF21 in IBD patients could be reproduced in murine experimental models of colitis." (PMID 28584524, 2017). "Colitis-induced FGF21 expression may subsequently activate lipolysis in WAT and weight loss." (PMID 38983722, 2024). "This relationship between FGF21, adiponectin, and insulin might explain the changes in their levels observed in FMT-colitis group mice in this study, which were declines in FGF21 and adiponectin accompanied by elevated plasma insulin level and decreased insulin signaling in adipose tissue." (PMID 36735734, 2023). "Therefore, FGF21 KO mice may maintain goblet and Paneth cell homeostasis in colitis through the activation of IL-22-STAT3 signaling." (PMID 37432218, 2023). "It has been shown that dextran sulfate sodium-induced colitis resulted in increased expression of FGF21, while the absence of FGF21 alleviated colitis symptoms, reduced adipose tissue lipolysis and prevented weight loss." (PMID 38983722, 2024). "However, the effects of exogenous FGF21 treatment on acute and chronic colitis and colitis recovery have not been adequately examined so far." (PMID 38983722, 2024). "We showed that absence of FGF21 attenuates experimental colitis-induced adipose tissue lipolysis, and the effect may be mediated by IL-6 pathway." (PMID 28584524, 2017). "In addition, experimental colitis markedly reduced eWAT/body weight ratio and eWAT adipocyte size in WT mice, but not in FGF21-KO mice." (PMID 28584524, 2017). "Additionally, we also measured the hepatic expression of FGF21, a hepatokine that regulates glucose and lipid metabolism, and observed that its levels of mRNA and protein expression were significantly diminished in FMT-colitis group mice compared to FMT-control group." (PMID 36735734, 2023). "Although the effects of exogenous FGF21 treatment on acute and chronic colitis and colitis recovery and remission were not clearly investigated due to the complex effects of FGF21, we propose that targeting the FGF21 signaling pathway could be a promising strategy for treating IBD." (PMID 37432218, 2023).
hypothyroidism (7 papers, 2021 to 2024). Abnormally low levels of thyroid hormone. "Further studies with a larger number of young patients with severe hypothyroidism are needed to confirm the association between FGF-21 levels and thyroid function." (PMID 34946319, 2021). "However, it was not firmly established that there is a clear association between the rise in FGF-21 levels and the change in metabolic parameters in patients with hypothyroidism." (PMID 34946319, 2021). "The evaluation of the effect of oxidative stress on FGF21 levels during the development of hypothyroidism and after starting levothyroxine treatment in HT seems to be a promising scientific target." (PMID 39452947, 2024). "Instead, we observed a significant rise of FGF21 serum level in conditions of metabolic challenge of rapid-onset hypothyroidism after RAI treatment." (PMID 35909532, 2022). "There was a transient increase in FGF21 serum level during rapid-onset hypothyroidism following radioiodine treatment." (PMID 35909532, 2022). "In radioiodine-induced hypothyroidism, the rising serum FGF21 concentration correlated positively with rising serum triglycerides and negatively with falling SHBG, reflecting increased hepatic lipogenesis." (PMID 35909532, 2022). "In this study, plasma FGF-21 levels of the group with hypothyroidism were measured significantly higher after LT4 treatment compared to baseline." (PMID 34946319, 2021). "However, in another study focused on adults, mean plasma FGF-21 concentrations were significantly higher in subjects with overt hypothyroidism than in subjects with either euthyroidism or subclinical hypothyroidism." (PMID 34946319, 2021). "However, there was a significant transient increase in FGF21 serum levels in rapid-onset hypothyroidism in comparison to hyperthyroid and euthyroid phase [median 160.55 (interquartile range, 92.48-259.35) vs 119.55 (67.78-192.32) and 104.43 (55.93-231.93) pg/mL, P=0.034 and 0.033, respectively]." (PMID 35909532, 2022). "Another study has found that circulating FGF-21 concentrations were significantly increased in hypothyroidism patients which were closely correlated with the serum concentrations of thyroid-stimulating hormone, suggesting that thyroid-stimulating hormone could also regulate FGF-21." (PMID 34784265, 2022). "In this setting, FGF21 serum level positively correlated with rising serum triglycerides, and negatively with SHBG, which was typically reduced in hypothyroidism." (PMID 35909532, 2022). "Now that it has been firmly established that FGF-21 is associated with serum lipid metabolism, recent focus is shifting towards elucidating the relationship between FGF-21 and the alterations of serum LDL-C in patients with hypothyroidism." (PMID 34784265, 2022). "Discrepancies among different reports can be attributed to differences in study design, population age ranges, the severity of hypothyroidism, and technical aspects of different FGF-21 Elisa kits used for plasma or serum FGF-21 measurements." (PMID 34946319, 2021). "As reported, studies have shown that the serum FGF-21 concentrations were significantly lower in hypothyroidism patients whereas increased or did not change in patients with hyperthyroidism." (PMID 34784265, 2022). "Thus, TG and FGF-21 are found as much less sensitive markers than TSH (56.67 vs. 53.33 vs. 93.33, respectively) in the context of hypothyroidism." (PMID 34946319, 2021). "However, our results, together with the limited data available in the literature, raise the question of whether the length of hypothyroidism, the duration of LT4 supplementation, and the presence of autoimmune processes play a role in FGF21–thyroid interplay." (PMID 39452947, 2024). "A ROC curve analysis for FGF-21, TG, and TSH in the AIT treatment and control group was also performed in order to explore further if only FGF-21 and TG compared to TSH could serve as relative sensitive markers of peripheral hypothyroidism." (PMID 34946319, 2021).
hypothyroidism (continued). "In rapid-onset hypothyroidism after RAI treatment, rising FGF21 serum concentration was not accompanied by augmented adiponectin secretion." (PMID 35909532, 2022). "The decrease in serum FGF-21 levels in children and adolescents with AIT and subclinical hypothyroidism is not so evident as in the case of overt hypothyroidism due to Hashimoto’s thyroiditis." (PMID 34946319, 2021).
prostate carcinoma (7 papers, 2021 to 2025). A carcinoma that arises from epithelial cells of the prostate gland. "In vitro treatment with FGF21 also led to the suppressed proliferation of prostate cancer cells and induction of autophagy." (PMID 35321438, 2022). "FGF21 expression was decreased in clinic prostate cancer tissues, and overexpression of FGF21 inhibited prostate cancer cell viability." (PMID 36263162, 2022). "Although key adipocytokines known to play a role in prostate cancer include leptin, adiponectin, visfatin, fibroblast growth factor 21 (FGF21), and bone morphogenetic proteins (BMPs), there is a paucity of prognostic studies exploring the relationship between adipocytokine-related genes and PCa." (PMID 39524226, 2024). "In addition, in vivo FGF21 administration has been reported to inhibit the growth of prostate cancer which was accompanied by autophagy induction." (PMID 35321438, 2022). "We aimed to investigate the action of FGF21 in the development of prostate cancer (PCa)." (PMID 33753729, 2021).
rheumatoid arthritis (7 papers, 2015 to 2025). A chronic, systemic autoimmune disorder characterized by inflammation in the synovial membranes and articular surfaces. "When FGF21 is administrated to rheumatoid arthritis model mice, the levels of some antioxidant proteins, including SODs, increase, which in turn reduces oxidative stress and inflammation." (PMID 35159314, 2022). "Circulating FGF21 levels are known to be increased in patients with rheumatoid arthritis." (PMID 35159314, 2022). "Serum FGF21 levels are also higher in seropositive rheumatoid arthritis (RA) compared with seronegative RA." (PMID 26441837, 2015). "FGF21 has demonstrated the capacity to mitigate arthritis severity through the suppression of humoral and cellular immune responses, as well as by dampening the expression of pro-inflammatory cytokines in the cases of rheumatoid arthritis (RA)." (PMID 38155961, 2023).
viral infection (7 papers, 2013 to 2025). "The hormone fibroblast growth factor 21 (FGF21) is induced in murine liver in response to both bacterial and viral infection." (PMID 40996795, 2025). "Conversely, pharmacologic administration of FGF21 after viral infection protected mice against these pathologic changes." (PMID 40996795, 2025). "This study provided evidence for new research directions regarding the role of FGF21 in viral diseases and its application in BVD adjuvant therapy and prevention and control." (PMID 36968461, 2023). "Although TRIB3 has been reported to negatively regulate FGF21 promoter activity under nutrient deprivation conditions, its relevance to viral infection is unknown." (PMID 39211324, 2024). "Currently, few studies have reported on FGF21 in viral diseases." (PMID 36968461, 2023). "Other metabolic factors, including FGF21, BMP7, and GDF15, trended up upon virus infection, presumably due to a compensatory effect as these three secreted proteins were involved in positively maintaining metabolic homeostasis." (PMID 34916489, 2021).
alcohol (6 papers, 2016 to 2025). "Studies found that BDNF and FGF21 are associated with alcohol dependence and impulsivity." (PMID 38721616, 2024). "We investigated the effects of BDNF rs6265 and FGF21 rs11665896 on impulsivity with alcohol dependence during withdrawal." (PMID 38721616, 2024). "In addition, alcohol-induced inflammation and fibrosis can enhance the expression of FGF21." (PMID 40786112, 2025). "As plasma ethanol clearance was not affected in liver-specific FGF21- or neuron-specific KLB-deficient mice, the FGF21-KLB axis is suggested to counteract alcohol intoxication without modulating alcohol catabolism." (PMID 37260446, 2023). "The evaluation of dysfunctional psychological, psychophysiological and neuroendocrine feedback regulation factors including FGF21 levels with ETG levels, cognitive and personality structure impairments could be a change towards a contemporary standardized alcoholism evaluation." (PMID 33330965, 2021).
angina (6 papers, 2017 to 2024). "In our study, we found that a high FGF21 level was significantly associated with all-cause mortality in stable angina patients which similar to previous observations." (PMID 36180826, 2022). "Third, the long-term prognosis of angina pectoris was not evaluated; thus, a well-controlled longitudinal study is needed to determine the causality between FGF21 level and the development of angina pectoris." (PMID 30185439, 2018). "Next, to determine the independent predictors of the risks of angina pectoris, we performed multiple logistic regression analyses to determine the associations of FGF21 with the incidence of stable and unstable angina." (PMID 30185439, 2018). "FGF21 was independently associated with the presence of angina pectoris (OR: 1.752; 95% CI: 1.081–2.839; P=0.023), and UAP (OR: 2.781; 95% CI: 1.476–5.239; P=0.002) after adjusting for gender, age, and BMI." (PMID 30185439, 2018). "Thus, the present study aimed to examine the levels of FGF21 amongst patients with SAP, UAP, and control subjects; and further determine the associations between serum FGF21 and the presence of angina pectoris, including both SAP and UAP." (PMID 30185439, 2018). "The largest subgroup consisted of 25 patients (45.45%) with unstable angina, where the mean FGF21 level was notably higher at 456.28 pg/mL." (PMID 39194718, 2024). "In our study, we provided evidence that the circulating level of FGF21 was higher in patients with unstable angina, similar to the findings of Cheng J and colleagues." (PMID 39194718, 2024). "This study indicates that plasma FGF21 is associated with a wide QRS complex and prolonged corrected QT interval in patients with stable angina." (PMID 36180826, 2022). "This study indicates that plasma FGF21 is associated with wide QRS complex and prolonged corrected QT interval in stable angina patients, further study is required to investigate the role of plasma FGF21 for the underlying pathogenesis." (PMID 36180826, 2022). "Second, it is a cross-sectional study, and hence the casuality between FGF21 level and the incidence of angina pectoris cannot be implied." (PMID 30185439, 2018). "As there is increased risks of morbidity and mortality in angina pectoris, a better understanding of the relationships between FGF21 and the incidence of angina pectoris will be of great benefit." (PMID 30185439, 2018). "We tested blood samples from 50 patients with AMI and 43 patients with stable angina pectoris (sAP) for FGF21, fatty acid binding protein 4 (FABP4), a protein secreted from adipocytes in response to adrenergic lipolytic signal, and total and individual fatty acids." (PMID 31413360, 2019). "In conclusion, our present study is novel in showing that circulating FGF21 may be a novel biomarker for the presence of UAP independent of traditional risk factors of angina pectoris." (PMID 30185439, 2018). "The aim of the study was to investigate the relationship between plasma FGF21 and the QRS duration and QTc interval in patients with stable angina." (PMID 36180826, 2022). "Circulating FGF21 concentration was an independent predictor of CIN, renal function decline, and MACE in patients with stable angina undergoing CAG and/or PCI." (PMID 30127382, 2018). "The present study indicates that FGF21 has a strong correlation and precise predictability for increased risks of UAP, that is independent of traditional risk factors of angina pectoris." (PMID 30185439, 2018). "However, circulating levels of FGF21 in patients with angina pectoris have not been well investigated." (PMID 30185439, 2018). "Therefore, we hypothesized that FGF21 would affect CIN and subsequent renal function deterioration in patients with stable angina who had been exposed to contrast media." (PMID 30127382, 2018). "However, circulating level of FGF21 in patients with angina pectoris has not yet been investigated." (PMID 30185439, 2018).
chronic hepatitis B (6 papers, 2017 to 2026). "At the same time, this study also explored the value of FGF21 promoter methylation in disease diagnosis and prognosis, providing a theoretical basis for evaluating the antiviral treatment effect and disease progression of chronic hepatitis B." (PMID 41258710, 2026). "Finally, FGF-21 levels are reported to increase in acute liver injury, but decrease in chronic hepatitis B patients, especially those with advanced fibrosis." (PMID 32235473, 2020). "This study aims to explore the clinical significance of fibroblast growth factor 21 (FGF21) in the development and progression of chronic hepatitis B (CHB)." (PMID 41258710, 2026). "Interestingly, serum FGF21 levels and biochemical markers of liver injury were significantly higher in acute hepatitis B (AHB) infection and significantly lower in chronic hepatitis B (CHB) patients in comparison to the control group." (PMID 39941067, 2025).
infarction (6 papers, 2015 to 2025). A localised pathological necrosis of tissue resulting from obstruction of the blood supply usually by a thrombus, an embolus, or vascular torsion. "To study how FGF21 acts on the infarction’s size, we used immunofluorescence and WB analyses to study the changes in astrocytes and inflammatory cytokines (NF-κB) in the infarction and surrounding areas in different groups." (PMID 35096806, 2021). "On the 7th day, FGF21 levels were significantly higher in the patients who subsequently developed re-infarction within 30 days than in the patients who did not develop re-infarction (with vs. without re-infarction: 0.45 (0.22–0.64) vs. 0.21 (0.15–0.29) ng/mL, P = 0.014)." (PMID 26091256, 2015).
MELAS (6 papers, 2020 to 2025). "All together, these two phenotypic subgroups, i.e. patients with tRNA point mutations (MELAS and MERRF), confirm that mtDNA translation defects are hallmarked by FGF21 and GDF-15." (PMID 32851462, 2020). "Our results confirmed the association between FGF21/GDF-15 and mitochondrial diseases due to translation defects (MELAS and MERRF) with skeletal muscle involvement." (PMID 32851462, 2020). "We evaluated the correlations between FGF21 and GDF15 and various phenotypes/genotypes, including syndromic/non-syndromic PMDs, different mitochondrial syndromes (MELAS, Leigh syndrome, etc.), nDNA/mtDNA pathogenic variants, gene functions, and different organ/system involvement." (PMID 35498801, 2022). "However, there was a tendency for higher CHIT1 concentrations in patients with central nervous system involvement (MELAS syndrome), while FGF21 and GDF15 were not relevantly altered in these patients." (PMID 39891741, 2025). "Some studies found that GDF15 or FGF21 levels were higher in some specific phenotypes of PMDs, for example, in patients with TK2 defects, MELAS, or muscle manifestations." (PMID 35498801, 2022). "In this study, FGF21 and GDF15 were predominantly elevated in patients with a primary muscular phenotype (CPEO, CPEO-plus), while not significantly altered in mitochondriopathies with concomitant CNS manifestation (MELAS)." (PMID 39891741, 2025). "Previously, the fibroblast growth factor 21 (FGF21) and the growth differentiation factor 15 (GDF15) have been used as biomarkers for mitochondrial translation and mtDNA maintenance disorders, or mitochondrial encephalomyopathy, lactic acidosis and stroke-like episodes (MELAS), respectively." (PMID 39288270, 2024). "However, FGF-21 does not discriminate non-myopathic MD, such as LHON or sensorineural deafness, or disease progression in patients harboring the MELAS-associated m.3243A > G mutation." (PMID 34203775, 2021).